RPL31P10 (ribosomal protein L31 pseudogene 10)
Synonyms: RPL31_15_1198
Gene: Processed pseudogene on chromosome 12 (6,409,637 to 6,410,013, reverse strand). Ensembl gene ENSG00000213942.
Diseases named in the same sentence as RPL31P10 in open-access papers:
RPL31P10 is named in the same sentence as 1 disease in open-access papers, as found by Europe PMC text mining. Sharing a sentence is not in itself a finding about the gene and the disease.
RPL31P10 shares sentences with these, for which no sentence is quoted: ovarian carcinoma (1 paper).